CCDC60 (coiled-coil domain containing 60)
Synonyms: MGC39827
Tractability: No criterion of Open Targets' tractability assessment is met for any kind of drug.
Gene: Protein-coding gene on chromosome 12 (119,334,703 to 119,541,047, forward strand). Ensembl gene ENSG00000183273.
Gene Ontology:
Molecular function: protein binding
Genetic constraint (gnomAD): Loss-of-function variants: 40 observed, 48.98 expected, observed/expected ratio (o/e) 0.82, 90% interval 0.63 to 1.06. The upper end of that interval is the gene's LOEUF score, 1.06, which puts it in group 4 of 6, group 1 being the genes least tolerant of losing a copy. Missense variants: 536 observed, 598.09 expected, observed/expected ratio (o/e) 0.9, 90% interval 0.83 to 0.96. Synonymous variants: 181 observed, 215.95 expected, observed/expected ratio (o/e) 0.84, 90% interval 0.74 to 0.95.
Homologues: Orthologues: chimpanzee CCDC60 (99% identical), macaque CCDC60 (97% identical), pig CCDC60 (82% identical), dog CCDC60 (77% identical), mouse Ccdc60 (76% identical), rat Ccdc60 (76% identical), rabbit CCDC60 (72% identical), guinea pig CCDC60 (69% identical), tropical clawed frog ccdc60 (33% identical).
Diseases named in the same sentence as CCDC60 in open-access papers:
CCDC60 is named in the same sentence as 12 diseases in open-access papers, as found by Europe PMC text mining. Sharing a sentence is not in itself a finding about the gene and the disease. The quoted sentences say what the papers report.
head and neck squamous cell carcinoma (2 papers, 2023 to 2024). A squamous cell carcinoma that arises from any of the following anatomic sites: lip and oral cavity, nasal cavity, paranasal sinuses, pharynx, larynx, and salivary glands. "However, rarely reports have detected the function and underlying immune-related mechanism of CCDC60 in head and neck squamous cell carcinoma." (PMID 37064086, 2023). "For example, CCDC3 was found to be a nuclear tumor suppressor in breast cancers, and CCDC60 is a potential marker correlated with the prognosis of head and neck squamous cell carcinoma." (PMID 38540995, 2024). "Correlation of CCDC60 mRNA expression and clinical prognosis in head and neck squamous cell carcinoma with different clinicopathological factors by Kaplan–Meier plotter." (PMID 37064086, 2023). "However, the prognostic value of CCDC60 in head and neck squamous cell carcinoma (HNSC) and its function in tumor immunity remain unclear." (PMID 37064086, 2023).
bladder cancer (1 paper, 2023). "CCDC60 is a member of CCDC proteins family, which presents huge potential to inhibit tumor growth and mediate biological processes in many cancers, such as bladder cancer and gastric cancer." (PMID 37064086, 2023).
hemorrhagic disease (1 paper, 2021). Spontaneous or near spontaneous bleeding caused by a defect in clotting mechanisms (blood coagulation disorders) or another abnormality causing a structural flaw in the blood vessels (hemostatic disorders). "Most of these genes are known to be involved in the manifestation of various clinical phenotypes, such as metabolic diseases (CPT1B and BLVRA); hemorrhagic diseases (RUNX1 and GP6); and neuronal disorders (KCNAB3, FAM179B, CCDC60, GRM6, and PRDM8), among others." (PMID 34440289, 2021).
lymph node metastasis (1 paper, 2023). "Interestingly, in the subgroup of lymph node metastasis, CCDC60 expression was significantly lower in the N2 group than N0 group (P < 0.01)." (PMID 37064086, 2023). "qRT-PCR results indicated that in 15 pairs of HNSC samples without lymph node metastasis, CCDC60 mRNA expression was lower than that in adjacent healthy tissues." (PMID 37064086, 2023).
cancer (2 papers, 2023 to 2024). A tumor composed of atypical neoplastic, often pleomorphic cells that invade other tissues. "For example, CCDC60 is a member of the coiled-coil domain containing family, which takes part in the occurrence and development of many types of cancer." (PMID 38322990, 2024). "We realized that the expression level of CCDC60 mRNA was significantly downregulated in most types of cancers via the TIMER2.0 database (P < 0.05)." (PMID 37064086, 2023). "First, we applied the TIMER2.0 database to conduct pan-cancer analysis on the expression of CCDC60, and further confirmed the downregulated CCDC60 expression in HNSC tissues using the TCGA database (n= 546), compared with the healthy samples." (PMID 37064086, 2023). "Coiled-coil domain containing 60 (CCDC60) is a member of the CCDC family, which participates in the progression of many types of cancer." (PMID 37064086, 2023).
tumor (2 papers, 2023 to 2024). "We noticed that increased CCDC60 mRNA expression was linked with OS in male (HR = 0.560, P = 0.0024), white race (HR = 0.570, P = 0.0011) and tumor grade 3 (HR = 0.430, P = 0.0058)." (PMID 37064086, 2023). "As a tumor suppressor gene, CCDC60 was related to a longer prognosis and involved in regulating the immune infiltration and enhancing the response to immunotherapy of HNSC patients." (PMID 37064086, 2023). "Another focus of our study was on the function of CCDC60 in tumor immunity and its potential mechanism of immune regulation in HNSC." (PMID 37064086, 2023). "We identified the CCDC60-related co-expression genes, which were mainly enriched in the NOD-like receptor signaling pathway associated with the inhibition of tumor growth, leading to a better prognosis of HNSC patients." (PMID 37064086, 2023). "In the tumor grade subgroup, we noticed the increasing expression of CCDC60 with increasing tumor grade in HNSC patients." (PMID 37064086, 2023). "Correlation analysis between CCDC60 and related genes and markers of immune cells in Tumor Immune Estimation Resource (TIMER2.0)." (PMID 37064086, 2023). "These experimental data confirmed the results of bioinformatics analysis, suggesting that CCDC60 played a tumor suppressor role through the NOD-like receptor signaling pathway, leading to a longer prognosis of HNSC patients." (PMID 37064086, 2023). "Additionally, the connections between the expression of CCDC60 and tumor-infiltrating immune cells, immune marker sets, immunomodulators and chemokines in HNSC were explored." (PMID 37064086, 2023). "Together these findings suggest that CCDC60 might regulate the immune infiltration and improve the response to immunotherapy in HNSC patients, which has an important effect on the tumor microenvironment of HNSC." (PMID 37064086, 2023).
CCDC60 also shares sentences with these, for which no sentence is quoted: Alzheimer disease (1 paper); breast carcinoma (1); gastric cancer (1); metabolic disease (1); neurological disorders (1); schizophrenia (1).